MMP12 (matrix metallopeptidase 12)
Diseases named in the same sentence as MMP12 in open-access papers (continued):
Sharing a sentence is not in itself a finding about the gene and the disease.
breast carcinoma (21 papers, 2005 to 2025). "Whilst there was consensus in terms of fewer changes in stroma compared to tumor, only MMP12, previously associated with breast cancer poor prognosis, was detected as a BTNBC marker in both PDX mouse and patient stroma." (PMID 26980748, 2016). "In this study, we evaluated the association of these two common polymorphisms of the MMP12 gene with breast cancer risk and survival in the Shanghai Breast Cancer Study." (PMID 15987457, 2005). "This is the first report on the association of the MMP12 gene polymorphism with breast cancer risk and survival, and the results need to be confirmed in other large-scale studies." (PMID 15987457, 2005). "In addition, MMP-12 A1082G gene polymorphism G allele has associated with poorer prognosis of breast cancer patients." (PMID 40176865, 2025). "Most have been implicated in tumor biology, and many of these gene sets have been implicated in breast cancer progression, including chromosomal region 1p33, matrix metalloproteinases (including MMP12), and sequence targets of peroxisome proliferator-activated receptor alpha." (PMID 21627793, 2011). "Given the functional significance of this single nucleotide polymorphism and the role of MMP12 in breast carcinogenesis, we hypothesized that this single nucleotide polymorphism may be related to breast cancer risk and survival." (PMID 15987457, 2005). "The inhibitory potential of rosmarinic acid on MMP-1, MMP-2, MMP-9, and MMP-12 will limiting their ability to promote proliferation, invasiveness, angiogenesis, and metastasis of breast cancer cells." (PMID 40176865, 2025). "Studies have shown that CXCR4 mediates MMP12 to degrade the matrix, leading to breast cancer infiltration and growth." (PMID 35069702, 2021). "MMP12 had a significant relationship with the pathological stage of breast cancer patients, and patients with high expression levels of MMP12 had a poor prognosis." (PMID 35069702, 2021). "In humans, increased tumor sc-IgGs were found to be associated with poor breast cancer patient outcomes and high levels of MMP3-/MMP12-cleaved IgG were detected in sera from inflammatory bowel diseases patients, who did not respond to anti-TNFα therapy." (PMID 32117299, 2020). "Matrix metalloprotease 12 (MMP12), a protease that converts plasminogen to angiostatin (a potent inhibitor of angiogenesis), inhibits angiogenesis when overespressed in breast cancer tissue." (PMID 21627793, 2011). "Examination of breast cancer studies in the Oncomine database supports the possibility that CXCR4 can regulate MMP12 expression: MMP12 expression correlated significantly with CXCR4 expression, and not with CXCR7 expression." (PMID 22152016, 2011). "Some systematic reviews suggest that high expression of MMP-12 could be used as a biomarker for poorer prognosis due to shorter overall survival in breast cancer patient." (PMID 40176865, 2025). "In addition, MMP12 (β, 0.72 [95% CI, 0.09-1.35]; P = .03), a macrophage-secreted matrix metalloproteinase known to promote breast cancer progression, was elevated in Black women experiencing discrimination." (PMID 39951265, 2025). "The concentration of MMP-12 in WF from breast cancer patients with luminal subtypes tended to be higher than that with HER2 overexpression and basal subtype (luminal A 703.41 pg/ml, luminal B 789.91 pg/ml, HER2 overexpression 436.47 pg/ml and basal 344.45 pg/ml, P = 0.013)." (PMID 26313265, 2015). "Six of the 11 non-mitosis related genes were previously associated with poor survival in breast cancer patients: KRT17, MMP12, SLC7A5, SQLE, GABRP and PA2G4, but the remaining 5 had not been previously associated with cancer risk: CCDC86, NUP107, NUTF2, WASF1 and ELOVL6." (PMID 23077491, 2012).
breast carcinoma (continued). "Evaluation of breast cancer data present in the Oncomine database indicates that only MMP12 expression is significantly correlated with CXCR4 expression: from the nine breast cancer databases evaluated, the average correlation was 0.31 with an average P value for the correlation of less than 0.04." (PMID 22152016, 2011). "Likewise, MMP-12 could be a benign prognosis index, because the concentrations of MMP-12 in WF from the breast cancer patients with luminal subtypes tended to be higher than that with HER2 overexpression and basal subtypes." (PMID 26313265, 2015). "This study suggests that two common polymorphisms (A-82G and A1082G) of the MMP12 gene may not be related to breast cancer risk." (PMID 15987457, 2005). "Our study suggests breast cancer risk may not be associated with the A-82G and A1082G polymorphisms in the MMP12 gene." (PMID 15987457, 2005). "Among those 11 protein candidates, we found 6 proteins that are involved in the progression and development of breast cancer, those are MMP-1, MMP-2, MMP-9, MMP-12, M-phase inducer phosphatase-2 (CDC25B), and Aldose reductase." (PMID 40176865, 2025). "These compounds are predicted to stably interact with the MMP12, CDK4, JAK3, VEGFR2, MMP13, VEGFR1, and KCNA3 proteins, which have a role in inhibiting the growth and inducing apoptosis in breast cancer cells." (PMID 36106139, 2022). "The results showed that MMP9, MMP12, MMP15, and MMP27 groups were all highly variable (p < 0.01), whereas the other groups were not markedly different, indicating that these genes may play important roles in the occurrence and development of breast cancer." (PMID 35069702, 2021). "Kalembeyi and colleagues demonstrated up-regulation of MMP-9 expression in mouse mammary carcinoma cells in response to exogenous TNC, while a recent study reported that the invasion-promoting effect of TNC on glioma cells is mediated through up-regulation of MMP-12." (PMID 19405959, 2009).
ischemic stroke (21 papers, 2014 to 2026). A stroke disorder caused by obstruction of blood flow to the brain, due to thrombotic (local blood clot formation) or embolic (due to a blood clot or other material traveling from another site) event. "Using different databases, it found that lower serum levels of MMP-12 were associated with an increased risk of ischemic stroke." (PMID 38697862, 2024). "The first study examined the causal effects of MMP-1, MMP-8, and MMP-12 levels on ischemic stroke." (PMID 38697862, 2024). "In conclusion, we found causal evidence supporting three classic genes MMP12, F11 and SCARA5, and three novel genes SH3BGRL3, SWAP70 and SPATA20 were associated with the risk of ischemic stroke and their subtypes." (PMID 41488603, 2026). "Elected levels of MMP12 after ischemic stroke was reported to degrade several tight junction proteins including claudin-5, occludin and ZO-1." (PMID 35382832, 2022). "We conclude that suppressing MMP-12 after an ischemic stroke is a promising therapeutic strategy for promoting the recovery of neurological function." (PMID 36267234, 2022). "This study highlights the enhanced neurological and functional recovery after an ischemic stroke when MMP-12 expression is suppressed." (PMID 36267234, 2022). "In this study, we showed that a gene-silencing treatment (M12sh) that blocks MMP-12 elevation in the ischemic brain promotes neurological and functional recovery in young male and female rats following an ischemic stroke." (PMID 36267234, 2022). "Overall, our results indicate that MMP-12 expression increases in the brain following an ischemic stroke, and that M12sh treatment immediately following acute ischemia is effective in preventing this increase." (PMID 36267234, 2022). "Although various brain cells (neurons, oligodendrocytes, and microglia) express MMP-12 in the brain following an ischemic stroke, the primary source of MMP-12 is the monocytes/macrophages that have infiltrated into the ischemic brain." (PMID 36267234, 2022). "The results of this study indicate a pathological role for MMP-12 in ischemic stroke and highlight a potential therapy to mitigate the damage after ischemic stroke by reducing MMP-12 expression." (PMID 25955565, 2015). "Our results further strengthen this observation and demonstrate the importance of silencing MMP-12 by administering MMP-12 shRNA expressing plasmids in order to achieve a significant neuronal protection after ischemic stroke." (PMID 25955565, 2015). "It found that lower serum levels of MMP-12 were associated with an increased risk of ischemic stroke, lower serum levels of MMP-1 and MMP-12 were linked to an increased risk of large-artery stroke, and higher serum levels of MMP-8 were associated with an increased risk of small vessel stroke." (PMID 38697862, 2024). "The overall findings of this study strongly support the hypothesis that suppressing MMP-12 after an ischemic stroke improves neurological and functional recovery." (PMID 36267234, 2022). "The improved neurological and functional outcomes following ischemic stroke observed in this study may be attributable to acute MMP-12 suppression." (PMID 36267234, 2022). "In addition, MMP12 and HDAC9 gene expression levels were associated with risk of ischemic stroke, and inhibition of the expression of these genes inhibited plaque development and promoted plaque stability." (PMID 35842645, 2022). "Elevated MMP-12 after ischemic stroke disrupts the BBB by degrading tight junction proteins." (PMID 30131754, 2018). "This study highlights the possible pathological role of MMP-12 in the context of ischemic stroke." (PMID 25955565, 2015). "This is the first study to explore the deleterious role of MMP-12 after ischemic stroke." (PMID 25955565, 2015).
ischemic stroke (continued). "TIMP1 unfolds protective neurovascular effects in ischemic stroke, whereas both MMP12 and osteopontin receptor CD44 may critically contribute to ischemic brain damage, suggesting that these proteins/genes may all be important therapeutic targets in ischemic stroke." (PMID 35752654, 2022). "However, the finding of their decreased levels in patients with preoperative symptoms is not in line with recent reports of overexpressed MMP-12 in atherosclerotic plaques associated with ischemic stroke." (PMID 25803692, 2015). "In animal models of ischemic stroke, the expression of MMP‐12 in the brain is significantly increased, and inhibition of MMP‐12 can reduce brain damage and promote the prognosis of neurological, sensorimotor, and cognitive functions." (PMID 37905592, 2023). "Therefore, MMP‐12 may be a potential target for the treatment of ischemic stroke." (PMID 37905592, 2023). "Recently, we demonstrated the upregulation of matrix metalloproteinase-12 (MMP-12) in the ischemic brain of young rodents during both the acute and chronic phases following an ischemic stroke." (PMID 36267234, 2022). "The 21 ischemic stroke genes overlapping with genes that code for ECM-related proteins included COL3A, MMP1, MMP12 and MMP3." (PMID 33730931, 2021). "We also found genetically higher matrix metalloproteinase-12 (MMP12) to be protective of coronary heart disease, MI, and ischemic stroke." (PMID 33210602, 2020). "Although different types of MMPs act differently, there is accumulating evidence that MMP-2, MMP-9, and MMP-12 are involved in the pathogenesis of BBB disruption and cerebral edema formation during ischemic stroke." (PMID 30131754, 2018). "In the present study, continued MMP-12 suppression neither enhanced nor diminished the neurologic functional benefits of acute MMP-12 suppression, suggesting that chronic suppression of MMP-12 after ischemic stroke is not detrimental to recovery." (PMID 36267234, 2022). "Furthermore, recent studies have reported TWEAK, matrix metallopeptidase 12, CD40, and scavenger receptor class A member 5 as promising targets for the treatment of ischemic stroke." (PMID 33263724, 2021). "Unlike other MMPs, the benefits of MMP-12 suppression may not be temporally limited to a specific time frame and because MMP-12 may only have a pathological function during ischemic stroke and recovery." (PMID 36267234, 2022).
Obesity (21 papers, 2012 to 2026). Accumulation of substantial excess body fat. "MMP12 expression is associated with metabolic dysfunction and, in contrast to our findings here, was reported to be elevated in obesity, which contributes to alterations in the extracellular matrix (ECM)." (PMID 39858399, 2024). "In this study, variants in MMP7 (-181G) and MMP12 (-82G) were also associated with obesity and its severity." (PMID 37445827, 2023). "Regarding the roles of macrophages and fibroblasts in governing pioglitazone-prevented aortic stiffening caused by obesity, we found that pioglitazone effectively suppressed Ctss and Mmp12 in macrophages and fibroblasts." (PMID 33781257, 2021). "MMP-3 Lys45Glu (A/G), MMP-7 (-181A/G), and MMP-12 (-82A/G) variants were associated with obesity and its anthropometric indicators." (PMID 29317790, 2017). "There have been reports linking Mmp12 to kidney damage associated with obesity." (PMID 38674390, 2024). "The aims of the current study were, therefore, to assess the impact of MMP-1-519A/G (rs1144393), MMP-1 -1607 1G/2G (rs1799750), MMP-3Lys45Glu (A/G) (rs679620), MMP-7 -181A/G (rs11568818), and MMP-12 -82A/G (rs2276109) polymorphisms on obesity status and its anthropometric indicators." (PMID 29317790, 2017). "MMP-3, MMP-7, and MMP-12 polymorphisms associate with obesity risk and its severity." (PMID 29317790, 2017). "The present study investigated the MMP-12 function in obesity-induced glomerular fibrogenesis and inflammation in mice lacking apolipoprotein E alone (apo E−/−)—which are predisposed to obesity—or both apo E and MMP-12 (apo E−/−MMP-12−/−) that were maintained on HFD for 3, 6, or 9 months." (PMID 26822129, 2016). "Collectively, these findings suggest that MMP12 levels and infiltration of macrophages were diminished in the aortas of Fsp27AKO mice in obesity-related AAA." (PMID 39872985, 2025). "Adipose tissue-associated macrophages produce elastase MMP12—one of the targets of TIMP1 and coincidentally a marker of inflammatory response during obesity." (PMID 37432145, 2023). "Other BMs revealed to be associated with obesity-related HF are suggestive of mechanisms associated with apoptosis (TNFRSF10A), inflammation (ST6GAL1 and GAL-9) and fibrosis (MMP12, TIMP1 and QPCT)." (PMID 35945262, 2022). "The impact of MMP-1 (-519A/G, -1607 1G/2G), MMP-3 Lys45Glu (A/G), MMP-7 -181A/G, and MMP-12 -82A/G variants and plasma MMP levels on obesity and microvascular reactivity in Tunisians." (PMID 29317790, 2017). "Individuals carrying the MMP-3 45G or MMP-12 -82G variants were also associated with a higher risk for severe forms of obesity (MMP-3: OR = 1.9, P = 0.002; MMP-12: OR = 2.63, P = 0.003)." (PMID 29317790, 2017). "Among MMPs, MMP-1, MMP-3, MMP-7, and MMP-12 genes have been found to affect adipose tissue remodeling and obesity-related metabolic traits." (PMID 29317790, 2017). "In a similar manner, increased levels of MMP-12 were found in mice with a diet-induced obesity and its expression colocalized in adipocytes and adipose tissue macrophages." (PMID 29317790, 2017). "The goals of the current report were to explore the impact of MMP-1 (-519A/G; -1607 1G/2G), MMP-3 Lys45Glu (A/G), MMP-7 -181A/G, and MMP-12 -82A/G SNPs on the development of obesity and its severity among Tunisians." (PMID 29317790, 2017). "Both Mmp12 and Mmp13 have been recently shown to be elevated in the liver in other models of diet induced obesity as well." (PMID 25880591, 2015). "Mmp2, 3, Mmp12 and Mmp13 are reportedly positively correlated with the degree of obesity and were up-regulated in the visceral WAT of HFD fed mice." (PMID 22947075, 2012). "Analyses of visceral and subcutaneous white adipose tissue from mice and humans showed that MMP12 was upregulated in obesity at the mRNA and protein levels, which resulted in increased activity; this indicated that MMP12 may be a target for treatment and prevention of cardiometabolic diseases." (PMID 35842645, 2022).
Obesity (continued). "Confocal microscopy showed that the expression of CTSS and MMP-12 was upregulated in both aorta and PVAT by obesity but was attenuated by pioglitazone." (PMID 33781257, 2021). "We speculated that obesity-induced arterial remodeling is predominantly due to the CTSS and MMP-12 secreted from the cells in the local microenvironment within or surrounding the artery." (PMID 33781257, 2021). "PPARγ activation directly upregulated CTSS and MMP-12 expression in the cell types within the PVAT and aorta, accompanied by a reversal of elastin fiber fragmentation and a reduction of elastolytic activity in obesity." (PMID 33781257, 2021). "Nevertheless, we did not observe a relationship between rs2276109 and MMP-12 protein level, similarly to finding in obesity patients." (PMID 30658596, 2019). "Especially interesting and promising target molecules for obesity-derived implications in placenta could be CCL2, PRL, MMP12, TAC3, PRG2 and IGFBP1 that were the most dysregulated genes among our study group." (PMID 28125591, 2017). "The results support our hypothesis that MMP-12 modulates HFD-induced glomerular fibrogenesis and inflammation in a mouse model of obesity." (PMID 26822129, 2016). "However, in two animal models of genetic obesity (ob/ob and db/db) and in a HFD model, while mRNA levels for MMP2, MMP3, MMP12, MMP14, MMP19, and TIMP1 are robustly induced, MMP7 (and MMP3) transcripts are markedly reduced in obese visceral adipose tissue compared to lean tissue." (PMID 37445827, 2023). "Furthermore, we detected increased expression of the LAM marker MMP12 on mRNA and protein level in response to an overnight fast also in eWAT of lean, healthy mice, suggesting that fasting-induced LAM accrual is not dependent on prior established obesity." (PMID 38360943, 2024).